RN7SL404P (RNA, 7SL, cytoplasmic 404, pseudogene)
Gene: Miscellaneous RNA gene on chromosome 17 (64,871,504 to 64,871,784, reverse strand). Ensembl gene ENSG00000264840.
Homologues: Orthologues: chimpanzee Metazoa_SRP (96% identical), chimpanzee Metazoa_SRP (90% identical), macaque Metazoa_SRP (90% identical), macaque Metazoa_SRP (89% identical), rabbit Metazoa_SRP (67% identical). Paralogues in human: RN7SL199P (96% identical), RN7SL656P (96% identical), Metazoa_SRP (96% identical), RN7SL270P (95% identical), RN7SL1 (83% identical), RN7SL3 (83% identical), RN7SL2 (83% identical), RN7SL45P (80% identical), RN7SL566P (80% identical), RN7SL88P (80% identical), RN7SL113P (80% identical), RN7SL732P (80% identical), and 707 more.